DMRTC2 (DMRT like family C2)
Description:
May be involved in sexual development.
Synonyms: DMRT7
Tractability: No criterion of Open Targets' tractability assessment is met for any kind of drug.
Gene: Protein-coding gene on chromosome 19 (41,844,743 to 41,852,333, forward strand). Ensembl gene ENSG00000142025.
Subcellular location: Nucleus
Gene Ontology:
Molecular function: sequence-specific double-stranded DNA binding; DNA-binding transcription factor activity, RNA polymerase II-specific; RNA polymerase II cis-regulatory region sequence-specific DNA binding; double-stranded DNA binding; identical protein binding; sequence-specific DNA binding
Biological process: regulation of DNA-templated transcription; regulation of transcription by RNA polymerase II
Cellular component: chromatin; nucleus; XY body
Genetic constraint (gnomAD): Loss-of-function variants: 13 observed, 39.69 expected, observed/expected ratio (o/e) 0.33, 90% interval 0.21 to 0.52. The upper end of that interval is the gene's LOEUF score, 0.52, which puts it in group 2 of 6, group 1 being the genes least tolerant of losing a copy. Missense variants: 431 observed, 478.89 expected, observed/expected ratio (o/e) 0.9, 90% interval 0.83 to 0.98. Synonymous variants: 189 observed, 187.26 expected, observed/expected ratio (o/e) 1.01, 90% interval 0.9 to 1.14.
Homologues: Orthologues: chimpanzee DMRTC2 (99% identical), macaque DMRTC2 (96% identical), rat Dmrtc2 (82% identical), mouse Dmrtc2 (81% identical), dog DMRTC2 (80% identical), pig DMRTC2 (79% identical), guinea pig DMRTC2 (78% identical), Caenorhabditis elegans dmd-7 (16% identical), Caenorhabditis elegans dmd-9 (11% identical). Paralogues in human: DMRTC1 (26% identical), DMRTC1B (26% identical), DMRTA1 (24% identical), DMRT3 (22% identical), DMRTA2 (22% identical), DMRT2 (20% identical), DMRT1 (20% identical), DMRTB1 (14% identical).
Diseases named in the same sentence as DMRTC2 in open-access papers:
DMRTC2 is named in the same sentence as 3 diseases in open-access papers, as found by Europe PMC text mining. Sharing a sentence is not in itself a finding about the gene and the disease. The quoted sentences say what the papers report.
breast cancer (1 paper, 2025). A primary or metastatic malignant neoplasm involving the breast. "This study hypothesized that epigenetic processes, including DNA methylation, influence the expression of identified CG or testis-specific genes, such as SYCP1, ADAD1, SYCE1, PRSS54, DMRTC2, and TEX101, in breast cancer (BC), normal breast (NB), and chronic myelogenous leukemia (CML) cell lines." (PMID 41411337, 2025).
leukemia (1 paper, 2025). A malignant (clonal) hematologic disorder, involving hematopoietic stem cells and characterized by the presence of primitive or atypical myeloid or lymphoid cells in the bone marrow and the blood. "We comprehensively analyzed differential methylation, survival analysis (Kaplan-Meier), correlation (Spearman’s), and pathway enrichment analysis (GO/KEGG) of CG genes (SYCP1, ADAD1, SYCE1, PRSS54, DMRTC2, and TEX101) in BC and leukemia." (PMID 41411337, 2025). "In leukemia versus healthy donors, GO enrichment revealed that TEX101, ADAD1, PRSS54, and SYCE1 were the most enriched genes, whereas SYCP1 and DMRTC2 exhibited minimal enrichment." (PMID 41411337, 2025).
DMRTC2 also shares sentences with these, for which no sentence is quoted: colon cancer (1 paper).